IL9 (interleukin 9)
Diseases named in the same sentence as IL9 in open-access papers (continued):
Sharing a sentence is not in itself a finding about the gene and the disease.
diabetes (11 papers, 2012 to 2025). "Furthermore, shifts in TNFa and IP-10 at T4 and sCD40L, IL-9, and IL-13 at T0 were associated with diabetes mellitus progression with impaired glucose tolerance." (PMID 37629267, 2023). "IL-9 has been shown to promote IL-5 and IL-13 signaling, which have already been demonstrated to improve insulin sensitivity during diabetes." (PMID 40962954, 2025). "In summary, our results signify a role for IL-9 in mediating the protective effects of LsAg on diabetes." (PMID 40962954, 2025). "Although there are two reports describing IL-9 levels in type 2 diabetes patients, these reports are inconclusive, with one showing decreased IL-9 levels and another demonstrating increased IL-9 levels in diabetes patients." (PMID 40962954, 2025). "Although historically overshadowed by Th1/Th2 cytokines in the context of T1D, recent research has begun to explore IL-9’s potential role in the immunopathogenesis and complications of diabetes." (PMID 40804870, 2025). "While IL-9 levels are lower in pre-diabetes, LTBI infection increases the level of this cytokine under conditions of co-morbidity." (PMID 38327565, 2024). "With respect to adaptive immune cytokines, while IFN-γ levels are significantly increased, IL-9 levels which remain low during incipient diabetes increased and reaches normal values." (PMID 38327565, 2024). "In vitro studies of cultured podocytes and studies of IL-9 gene deletion in murine models of diabetes can address these limitations." (PMID 35445345, 2022). "We have reported that urinary IL-9 levels are higher in adolescents with T1D compared to healthy age-matched subjects, but there is a paucity of data on urinary levels of IL-9 in diabetes." (PMID 35445345, 2022). "Out of all the cytokines, chemokines, and defensins secreted, diabetes specifically altered antigen-induced secretion of IL-12, IL-9, and SDF-1." (PMID 34566972, 2021). "Parameters such as FIGO stage, IL9 score, Vδ2 + γδT cell infiltration, classification of differentiation, and diabetes mellitus were assigned a weighted number of points in the nomogram for a specific predicted 3-, 5- and 10-year overall survival (OS)." (PMID 33329510, 2020). "Moreover, an earlier report revealed reduced IL-9 levels in diabetes, and RNA sequencing data showed IL-9R expression in insulin target cells such as adipose tissue and the liver." (PMID 40962954, 2025). "In this study, we show that serum IL-9 levels are decreased in subjects with diabetes." (PMID 40962954, 2025). "Augmentation of IL-9 during pre-diabetes might indicates better mucosal immune response against M. tb infection, and this interesting hypothesis needs further validation." (PMID 38327565, 2024). "In the present study, diabetes augmented IL-9 secretion and increased Th9 population." (PMID 34566972, 2021). "Elevated IL-9 in DKD may reflect an attempt to mitigate chronic inflammation and fibrosis, suggesting its potential as both a biomarker and therapeutic target in the later stages of diabetes-associated kidney disease." (PMID 40804870, 2025). "Using Luminex multi-plex assays to assess cytokines (n = 29) and diabetes-associated proteins (n = 15) in healthy subjects, we observed that placing blood samples immediately on ice decreased the serum levels of several cytokines, including PAI-1, MIP1-β, IL-9, RANTES and IL-8." (PMID 33753773, 2021). "Thus, diabetes, by augmenting IL-9 and SDF-1, can promote chronic pathology in LF+ subjects." (PMID 34566972, 2021). "Additional insights come from studies examining IL-9 levels across different stages of glucose metabolism, including individuals with normal glucose tolerance (NGT), diabetes, and diabetic kidney disease (DKD)." (PMID 40804870, 2025). "With respect to adaptive immune cytokines, the increased levels of IL-17, seen during pre-diabetes, declines abruptly along with IL-2, IL-4, IFN-γ, while the IL-9 levels remain low." (PMID 38327565, 2024).
diabetes (continued). "Secretion of IL-27, IL-1Ra, IL-12, IL-33, IL-9, and SDF-1 was increased under diabetes conditions with increased Th9 polarization and increased expression of Cox-2 and IDO." (PMID 34566972, 2021). "Like IL-9, the basal level of SDF-1α was found to be significantly high in LF+ subjects with diabetes." (PMID 34566972, 2021). "Taken together, these findings indicate that IL-9 does not conform to traditional Th1/Th2 paradigms in diabetes." (PMID 40804870, 2025). "Despite the proven beneficial role of type 2 cytokines in diabetes and obesity, IL-9, a predominant Th2 cytokine, has not been investigated in this context." (PMID 40962954, 2025). "In our human cohort, we found decreased IL-9 levels in nonfilaria-infected patients with diabetes compared with the corresponding controls without diabetes." (PMID 40962954, 2025). "IL-9 levels were significantly lower in the uninfected diabetes subjects compared with their corresponding uninfected nondiabetic control group." (PMID 40962954, 2025). "In logistic regression models adjusted for treatment of diabetes conducted in the PSM cohort, IL-9 (OR 1.654, 95%CI 1.129–2.422, p = 0.010), IL-17 (OR 1.948, 95%CI 1.259–3.012, p = 0.003) and TNF-α (OR 1 2.051, 95%CI 1.286–3.272, p = 0.003) were independently associated with CAD." (PMID 39091640, 2024). "However, the serum levels of IL-9 were comparable between subjects with and without diabetes in the infected group." (PMID 40962954, 2025).
ulcerative colitis (10 papers, 2018 to 2025). An inflammatory bowel disease involving the mucosal surface of the large intestine and rectum. "Then, IL-9 is a pleiotropic cytokine that affects a variety of cells, and IL-9 and its receptors contribute to the pathogenesis of ulcerative colitis, which can further develop into cancer if left untreated." (PMID 38751718, 2024). "Jak3 knockout mouse model showing Il-2, Il-4, Il-7, Il-9, and Il-15 conduction defects, elevated levels of Il-6 and Il-17a and severe immunodeficiency, defects in barrier function lead to Ulcerative colitis (UC)." (PMID 33777833, 2021). "The percentages of PU.1+IL-9+Th9 cells are significantly increased in colonic lamina propria of patients with ulcerative colitis, especially in patients with active ulcerative colitis; IL-9 mRNA expression is also increased in inflamed colon samples from patients with ulcerative colitis." (PMID 31886308, 2019). "The role of Th9 and IL-9 in the pathogenesis of ulcerative colitis has been identified recently." (PMID 31886308, 2019).
influenza (9 papers, 2014 to 2025). An acute viral infection of the respiratory tract, occurring in isolated cases, in epidemics, or in pandemics; it is caused by serologically different strains of viruses (influenzaviruses) designated A, B, and C, has a 3-day incubation period, and usually lasts for 3 to 10 days. "Interestingly, a similar analysis on patient group infected with H1N1pdm09indicated that, while majority of cytokines clustered similar to the seasonal flu patients, a distinct group of cytokines including IL-1b, IL-9, IL-17 and VEGF clustered differently." (PMID 24505273, 2014). "Early secretion of Th17 (IL-8, IL-9, IL-17, IL-6) and Th1 cytokines (TNF-α, IL-15, IL-12p70) were detected in severe influenza patients, which were involved in cell-mediated immunity, may be associated with pathogenesis and autoimmune diseases induced by influenza." (PMID 40248710, 2025). "When comparing major trends between cytokeratins, CK8/18 and CK19 were the most similar, including the production of the anti-inflammatory cytokines IL-2, IL-9, IL-10, and TNF-β among influenza-infected (CK+FLU+ ) populations." (PMID 39791909, 2025). "Thus, increased IL-9 and IL-22 levels may indicate increased cellular regulatory functions in the immune response and activation of the innate mechanisms of the immune system in response to influenza vaccines, in particular, containing immunoadjuvants." (PMID 32695114, 2020). "Administration of the novel virus-like particle based vaccine elicited influenza-specific CD4+ and CD8+ T-cell responses and the induction of the cytokines IFN-γ, IL-17A, IL17F, IL-5, IL-13, IL-9, IL-10 and IL-21." (PMID 30573748, 2018). "In addition, IFN-λ increases influenza-induced Th1 cytokines (IFN-γ, IL6), whereas influenza-induced Th2 cytokines decrease (IL4, IL5, IL9, IL13)." (PMID 28293236, 2017).
Obesity (9 papers, 2010 to 2025). Accumulation of substantial excess body fat. "To better understand how IL-9 might affect the pathogenesis of diet-induced obesity and insulin resistance, we used mice deficient in IL-9/IL-9R signaling." (PMID 40962954, 2025). "In addition, results of clinical experiments showed that obesity and smoking, the risk factors for hypertension, could promote IL-9 expression." (PMID 32148441, 2020). "Taken together, our findings show that IL-9 signaling is protective against obesity and insulin resistance and that IL-9 mediates its effects on glucose homeostasis and inflammation by inhibiting the NLRP3 inflammasome." (PMID 40962954, 2025). "During diet-induced obesity in mice, the frequencies of IL-9 + CD4 + T cells and ILC2s and IL-9R expression on macrophages are significantly decreased." (PMID 40962954, 2025). "Taken together, during obesity, IL-9 production by CD4 + T cells and ILC2s and IL-9R expression on macrophages are significantly downregulated." (PMID 40962954, 2025). "Obesity was associated with higher levels of IL-12 (P40), MIP-1a in myocardial tissue, while KD alone was associated with higher levels of G-CSF, IL-9, MCP-1, MIP-1a, MIP-1b, RANTES, and TNF-α in myocardial tissue." (PMID 37686855, 2023). "Of the patients with hypertension, those with obesity and smoking habits exhibited higher IL-9 levels, whereas those with drinking habits and of male gender showed lower IL-9 levels." (PMID 32148441, 2020). "Considering that obesity and smoking were also closely related to inflammatory response, data of our clinical studies can also partly explain that IL-9 is involved in hypertension through inflammatory response." (PMID 32148441, 2020). "Furthermore, in this report, we show that helminth-mediated protection against obesity and insulin resistance is partially dependent on the IL-9 signaling pathway." (PMID 40962954, 2025). "Having observed decreased IL-9 levels during obesity, we next examined whether the administration of rIL-9 to HFD-fed WT mice might improve the hallmarks of insulin resistance, such as weight gain, impaired glucose tolerance and HFD-induced inflammation." (PMID 40962954, 2025). "With increasing quartiles of body fat, there was a significant decrease in the levels of IL-9, again indicating that IL-9 might play a protective role during obesity." (PMID 40962954, 2025). "In addition, we also demonstrated a potential role for IL-9 in the protective effects of helminth immunomodulation during obesity and insulin resistance in filaria-infected humans and in an animal model." (PMID 40962954, 2025). "The present study characterized the role of IL-9 signaling in obesity and metabolic dysfunction." (PMID 40962954, 2025). "We hypothesize that IL-9 plays a role in obesity-induced inflammation and thereby insulin resistance." (PMID 40962954, 2025). "Since most of our patients were women and sexual dimorphism could influence the effect of obesity on IL-9 levels, further studies in men are needed to better decipher the role of obesity in regulating IL-9 synthesis." (PMID 35807067, 2022). "Furthermore, in vivo macrophage depletion resulted in increased frequencies of ILC2s and eosinophils in the adipose tissue of HFD-fed IL-9R KO mice compared with PBS-treated controls, indicating that macrophages are the major target cell types of IL-9 during obesity." (PMID 40962954, 2025). "Obesity was associated with decreased serum levels of Eotaxin and KC, and elevated serum levels of G-CSF, TNF-α in offspring mice, while KD alone was associated with elevated serum levels of G-CSF, IL-1b, IL-6, RANTES, TNF-α and decreased serum levels of IL-1a, IL-9, IL-12 (p70)." (PMID 37686855, 2023). "Peripheral blood samples from validation cohort including 44 healthy children and 44 obesity children were used to evaluate concentration levels of MIP-1b, PDGF-BB, IP-10, IL-6, IL-9 and TNF-β." (PMID 40519917, 2025).
Obesity (continued). "The findings revealed that, in comparison to normal weight children, several cytokines, including MIP-1b, PDGF-BB, IP-10, IL-6, IL-9, and TNF-β, exhibited elevated levels in the serum of children with obesity." (PMID 40519917, 2025). "In the nvA(H1N1)-ARDS group, obesity and lymphocytopenia were more common and IP-10, interleukin (IL)-12, IL-15, tumor necrosis factor (TNF)α, IL-6, IL-8 and IL-9 were significantly increased versus control." (PMID 21062445, 2010). "Despite the proven protective roles of type 2 cytokines in obesity and insulin resistance, IL-9 signaling has never been investigated in this setting, except for one report showing reduced levels of IL-9 in type 2 diabetes patients." (PMID 40962954, 2025). "While demonstrating a novel mechanism by which IL-9 might mediate metabolic homeostasis and inflammation during insulin resistance and obesity, this study does not rule out further unidentified mechanistic roles for IL-9 signaling in mediating its effects." (PMID 40962954, 2025). "Our study provides evidence of low-grade chronic inflammation in women with PCOS independent of obesity as supported by an increase in 24 inflammatory parameters, 3 of which were demonstrated for the first time to be associated with PCOS: IL-9, MCP-3, and MIP-1α." (PMID 37893164, 2023). "Although numerous research had reported an increase in MIP-1b, IL-9 and TNF-β in obesity, our experimental findings suggest that the elevation of MIP-1b, IL-9 and TNF-β are not pronounced in the serum of obesity children." (PMID 40519917, 2025).
schistosomiasis (9 papers, 2017 to 2025). An infectious disease caused by parasitic trematodes of the genus Schistosoma that colonize human blood vessels and release eggs that can cause granulomatous reactions leading to acute (swimmer's itch or acute schistosomiasis syndrome) or chronic disease. "The direct correlation between the levels of IL-9 and IL-17 cytokines and the spleen size, portal vein diameter, and thickening of the periportal space reinforces the association of these cytokines with the immunopathogenesis of human schistosomiasis." (PMID 34970264, 2021). "Anti-IL-9 mAb therapy may be helpful in preventing inflammation-mediated liver damage caused by schistosomiasis." (PMID 28539607, 2017). "The genes with the largest literature were the Th2 cytokine genes originally identified by Marquet in SM1 (IL3, IL4, IL5, IL9, and IL13), that each had between 17 and 511 publications associated with schistosomiasis." (PMID 33659002, 2021). "Cytokines, such as IL-4, IL-10, IFN-γ, IL-17, and IL-9, have been reported to be key signals in the immune cells involved in schistosomiasis." (PMID 33628844, 2021). "Therefore, further studies are needed to clarify the defining roles of Th9 cells and IL-9 in the pathology of human schistosomiasis." (PMID 32132991, 2020). "Thus, the percentages of Th9 cells, the level of IL-9 and PU.1 all significantly elevated in mice with schistosomiasis, suggesting that the microenvironment induced by S. japonicum antigens favors Th9 proliferation and IL-9 secretion." (PMID 28646920, 2017). "In addition, dynamic changes of Th9 and IL-9 were synchronous with the developmental trend of hepatic egg granulomatous inflammation, suggesting that Th9 cells might be a new subset in the pathogenesis of schistosomiasis." (PMID 28646920, 2017).
tuberculosis (9 papers, 2012 to 2022). A chronic, recurrent infection caused by the bacterium Mycobacterium tuberculosis. "Increased expression of IL-9 may contribute to the development of TB, as it is associated with an impaired Th1 immune response in patients with tuberculosis." (PMID 23028695, 2012). "Although the roles of both IL-9 and IL-22 in the pathogenesis of both tuberculosis and SARS-CoV-2 remain unclear, both were upregulated in the superinfected mice at both time points, an outcome that warrants future studies." (PMID 36200898, 2022). "An in vitro study showed that increased expression of IL-9 may contribute to the development of tuberculosis." (PMID 34925358, 2021). "Findings from one in vitro study suggested that increased expression of IL-9 may contribute to the development of tuberculosis." (PMID 22363712, 2012). "Fractalkine, IL-17, IL-6, IL-9, MIP-1β, CRP, VEGF, and IL-5 levels in saliva and IL-6, IL-2, SAP, and SAA levels in serum were significantly higher in tuberculosis patients (P < 0.05)." (PMID 24327799, 2013). "Although the participation of Th9 cells in tuberculosis has not been reported in other studies, production of the cytokine IL-9 has been widely demonstrated in some studies." (PMID 26495323, 2015). "Newly discovered IL-9–producing CD4+ helper T cells (Th9 cells) have been reported to contribute to tissue inflammation and immune responses, however, differentiation and immune regulation of Th9 cells in tuberculosis remain unknown." (PMID 22363712, 2012).
breast carcinoma (8 papers, 2016 to 2025). "In solid tumors, IL9 promoted the growth of several types of pancreatic, colitis-associated, colon, or breast cancers by negatively regulating the antitumor function of T cells and promoting the immunosuppressive function of regulatory T cells." (PMID 36968220, 2023). "In breast cancer, the level of IL-9 is increased in the serum of patients and causes tumor metastasis." (PMID 32228589, 2020). "Because 4T1 breast cancer cells did not express IL9R on their surface, the therapeutic effect of IL9 therapy on macrophage-enriched 4T1 breast cancer was also evaluated." (PMID 36968220, 2023). "Other groups have reported that the IL–9 signaling pathway can have a role in breast cancer progression." (PMID 29725024, 2018). "Furthermore, increased IL-9 concentrations in peripheral blood of breast cancer patients promote cytotoxicity of tumor-specific CTLs." (PMID 39281678, 2024). "IL-9-producing CD8+ T cells highly express IL-2 and IL-17 in breast cancer and have low expression of the inhibitory receptors PD-1, KLRG1 and Tim-3." (PMID 32228589, 2020). "IL-9 and IL-21 can amplify the cytotoxic effect of CD8+ T cells, thus promoting an antitumor effect in breast cancer." (PMID 32228589, 2020). "Similarly, in lung and breast cancers, TH9 cells contribute to cancer progression by secreting IL-9." (PMID 39852828, 2025).
depression (8 papers, 2019 to 2025). "IL-9 has also been implicated in the pathophysiology of depression." (PMID 36614020, 2022). "Elevated IL-9 levels were found to correlate with maternal mid-pregnancy symptoms of depression and anxiety." (PMID 36614020, 2022). "In our review, we noticed that IL-9 decreased with the administration of the SSRI escitalopram (one study, moderate depression)." (PMID 40573262, 2025). "Three studies reported significant differences in inflammatory protein concentrations between MS participants with and without depression for IL-6 in serum, and IL-9,30 TNF-α and CRP in both serum and CSF." (PMID 39867847, 2025).